ALK (ALK receptor tyrosine kinase)
Diseases named in the same sentence as ALK in open-access papers (continued):
Sharing a sentence is not in itself a finding about the gene and the disease.
tumor (continued). "However, it has been reported that the overexpression of PD-L1 with TPS (Tumor Proportion Score) > 50% of tumor cells can be observed in tumors with ROS1 rearrangement and, less frequently, in tumors with rearrangements of ALK." (PMID 41303538, 2025). "Baseline molecular profiling was often mandatory in patients with non-squamous histology to exclude tumours that harbored an alteration in EGFR or ALK genes, while other more rare molecular alterations were not mentioned in the eligibility criteria." (PMID 40628491, 2025). "The next generation of ALK tyrosine kinase inhibitor, Brigatinib, has demonstrated significant efficacy in patients with ALK-positive NSCLC, offering clinical benefits in deep response of tumor, treatment of brain metastases patients, quality of life, and long-term survival." (PMID 40640095, 2025). "In LC, several driver genes involved in tumor progression also contribute to immune escape, including Kirsten rat sarcoma virus oncogene homolog (KRAS), epidermal growth factor receptors (EGFRs), and anaplastic lymphoma kinase (ALK)." (PMID 41009806, 2025). "In another large cohort, 100 of 1173 (8.53%) NSCLC patients’ tumor were identified as RDAA positive that does not have known and targetable EGFR/ALK/ROS1 mutation or rearrangement." (PMID 40246819, 2025). "All patients had high PD-L1 expression (Tumor Proportion Score ≥50%), and tested negative for activating mutations, such as EGFR mutations or ALK rearrangements." (PMID 40959419, 2025). "Among these, 28 tumours were anaplastic lymphoma kinase (ALK) positive and 11 ALK negative, and age <40 years, ALK-positive tumour status, and methotrexate-based chemotherapy were associated with improved survival." (PMID 41523563, 2025). "Validation on a comprehensive drug-testing platform demonstrated that ceritinib, unlike other ALK receptor tyrosine kinase inhibitors with lower prediction scores, inhibited tumor growth by targeting non-canonical kinases." (PMID 40968384, 2025). "Further, clinically approved EV liquid biopsy-based diagnostic tests such as ExoDx Prostate IntelliScore (EPI) and ExoDxTM Lung (ALK) do not purify tissue/tumour-derived EVs." (PMID 41193833, 2025). "Elevated ALK transcript levels were correlated with several adverse clinical features, including a PAX3/7–FOXO1-positive histology, an advanced tumor stage, and a larger tumor size at diagnosis." (PMID 40508013, 2025). "Mutations in additional RTK/RAS pathway genes, including ERBB4, ALK, and HRAS, may further contribute to tumor progression and therapeutic resistance." (PMID 40869017, 2025). "For instance, pH-responsive multifunctional DNA nanomaterials have been engineered as carriers for the controlled release of DOX and anaplastic lymphoma kinase (ALK)-specific siRNA, with low toxicity and commendable biocompatibility, thereby contributing effectively to tumor suppression." (PMID 40948789, 2025). "The tumor was negative for epidermal growth factor receptor (EGFR), anaplastic lymphoma kinase (ALK), ROS proto-oncogene 1 (ROS1) mutations and demonstrated a programmed death-ligand 1 (PD-L1) expression of 60%." (PMID 41304963, 2025). "ALK inhibitor crizotinib combined with anti-PD1 enhances T cell infiltration and promotes the accumulation of memory-like T cells, which significantly retards tumor growth and provides long-term immunity to inhibit tumor progression." (PMID 40051497, 2025). "Sequencing of the tumor revealed the lack of EGFR, KRAS or ALK mutations, rendering the patient ineligible for targeted therapy options." (PMID 41146188, 2025). "Finally, current treatments of primary or relapsed/refractory ALK-positive ALCL induce tumor cell death in an immunogenic fashion, thus enhancing the immune-mediated control of tumor growth." (PMID 41469691, 2025). "In ALK-negative tumours, alternative drivers have been identified, including ROS1, RET, NTRK3 and PDGFRB rearrangements or mutations." (PMID 40980125, 2025).
tumor (continued). "A Kirsten Rat Sarcoma Viral Oncogene Homolog (KRAS) exon 2 c.38G>A (p.G13D) mutation was detected in the tumor tissue, whereas mutations in the epidermal growth factor receptor (EGFR) and anaplastic lymphoma kinase (ALK) were negative." (PMID 40630489, 2025). "Although she was not eligible for targeted therapy due to the absence of actionable mutations such as ALK or EGFR, her tumor’s PD-L1 expression of 30% supported the use of immune checkpoint inhibitors." (PMID 41018467, 2025). "These indications can vary with regards to squamous or non-squamous NSCLC, tumour proportion score (TPS) (PD-L1 expression of ≥ 1%; 0–49%; or ≥ 50%), with or without EGFR/ALK mutations, first- or second line, mono- or combination therapy." (PMID 39212880, 2025). "Fourteen of 47 (30%) ALK+ ALCL patients died (median follow-up time, 33.8 months; range, 0.3–382.8 months): 5 of 9 (56%) patients with CD25-low neoplasms and 9 of 38 (24%) patients with CD25-high neoplasms." (PMID 40507248, 2025). "While ALK inhibitor treatment led to a reduction in phosphorylated AKT and the mTOR downstream target S6K1, AKT signaling was effectively reinduced following the cultivation of H2228 and H3122 tumor spheroids with CAF-CM." (PMID 40524253, 2025). "Individuals with tumor driver genes have been gradually revealed in NSCLC patients, with notable examples such as the epidermal growth factor receptor (EGFR) and the anaplastic lymphoma kinase (ALK)." (PMID 38238722, 2024). "The CheckMate 9LA study was a phase III trial evaluating a novel regimen in 1150 treatment-naïve NSCLC patients without known sensitizing EGFR/ALK genomic tumor aberration." (PMID 39410008, 2024). "Previous reports with a few references suggested that an ALK fusion was still present in SCLC components, indicating that tumor might be response for the next generation of ALK inhibitors." (PMID 38961982, 2024). "We were able to find a potential explanation for one, which was expressed in ALK-activated tumors (supported by one patient tumor and two PDXs but no other preclinical model)." (PMID 38898465, 2024). "The pathology showed the tumor cells to be positive for cytokeratin (CK), Vimentin, EMA, CD34, cyclinD1, negative for CK8, CK19, CK20, SMA, Desmin, S-100, CD117, Dog-1, Hepar-1, SOX-10 and ALK, and Ki-67 approximately 50%, which confirmed the diagnosis of SHC." (PMID 38552058, 2024). "Consistent with this, the MES phenotype has been associated with increased tumor relapse and therapeutic resistance, including the ability of NOR-to-MES reprogrammed cells to escape from ALK targeted therapies." (PMID 39133652, 2024). "Based on the ALK IHC results, only approximately 10% of the tumor cells were positive, whereas the remaining tumor cells showed no immunoreactivity." (PMID 39507756, 2024). "Importantly, the main limitation of this study is the low sample size of ROS1-, ALK- and RET-rearranged tumors, which is explained by the low prevalence of each tumor subtype." (PMID 39737401, 2024). "These tumor cells show immunopositively for CD30 and may show anaplastic lymphoma kinase (ALK) positivity or ALK negativity." (PMID 39347303, 2024). "The tumor stained positive for thyroid transcription factor 1 (TTF1), cytokeratin 7 (CK7), and Napsin A, but negative for CDX-2, cytokeratin 20, and anaplastic lymphoma kinase (ALK), and presented a wild-type epidermal growth factor receptor (EGFR)." (PMID 39594178, 2024). "Overall, this study shows that miR-1304-5p is an NB tumor suppressor and regulator of ALK TKI response, targeting oncogenic NRAS and paving the way for the use of miRNA- or FTI-based ALK TKI combination treatments for aberrant ALK-expressing NB." (PMID 38653965, 2024).
tumor (continued). "Results of immunohistochemical staining of tumor samples from HCC patients demonstrated a correlation between RNase1 expression and phospho-ALK expression in cancer cells and that ALK was expressed in most HCC cell lines." (PMID 38307859, 2024). "Besides its role in tumorigenesis, the Hippo pathway plays a pivotal role in drug resistance of NSCLC via crosstalk with other well-known tumor-promoting factors such as EGFR, ALK, BRAF, KRAS, and ROS1." (PMID 38499647, 2024). "Targeted inhibitors directed against specific mutated or rearranged oncogenes, such as epidermal growth factor receptor (EGFR), anaplastic lymphoma kinase (ALK), and receptor tyrosine kinase ROS proto-oncogene 1(ROS1) among others, exhibit promising anti-tumor activity." (PMID 39055566, 2024). "Knockdown of POSTN, but not FN1, significantly slows the migration rate of ALK/MYCN tumor cells in filling the wounded area." (PMID 38451815, 2024). "Owing to the tendency of ROS1 to be mutually exclusive with genes such as ALK, this study suggests that IHC can be used to screen tumor specimens negative for ALK expression before conducting FISH on specimens with positive IHC results." (PMID 38629293, 2024). "The CE-IVD IdyllaTM GeneFusion Assay (Biocartis, Mechelen, Belgium) is an RNA-based fully automated RT-PCR assay, designed to concurrently detect presence of ALK, ROS1, RET fusions and MET exon 14 skipping in formalin-fixed, paraffin-embedded (FFPE) tumor tissue sections." (PMID 38492039, 2024). "Firstly, the availability was limited to the treatment as monotherapy for patients with a tumor proportional score (TPS) of PD-L1 ≥ 50% without the driver mutations epidermal growth factor receptor (EGFR) and anaplastic lymphoma kinase (ALK)." (PMID 38601759, 2024). "EGFR gene mutations and ALK gene fusion are both important driver genes in NSCLC, typically not co-occurring in the same tumor." (PMID 39582541, 2024). "In the tumor samples available for immunohistochemistry, heterogeneous desmin positivity (12/13), inconstant MYOD1 (12/13) and myogenin (9/13) expression, and at least partial ALK (9/13) positivity were observed." (PMID 38168093, 2024). "Tecentriq is currently used in combination with Avastin (bevacizumab), paclitaxel and carboplatin (chemotherapy), for the initial (first-line) treatment of individuals with metastatic NSCLC with no EGFR or ALK genomic tumor aberrations." (PMID 38384472, 2024). "Immunohistochemistry revealed that the tumor cells were positive for alpha-smooth muscle actin (αSMA) and negative for S100, CD34, desmin, anaplastic lymphoma kinase (ALK), anti-pan cytokeratin antibody (AE1/AE3), and EMA, and the Ki-67 labeling index was approximately 50%." (PMID 39816285, 2024). "Secondly, our study did not detect other causes of tumor heterogeneity, such as EGFR-mutant or ALK-translocated." (PMID 39729352, 2024). "Development of drug resistance to ALK-TKI leads to hyperactivation and development of secondary mutations in kinases such as EGFR, ERBB3, it is therefore worth exploring further the combination of ALK-TKI and ERRB inhibitors to overcome any emerge resistance of these tumours." (PMID 39695132, 2024). "When the ALK-TKI was combined with a pan-HER inhibitor, afatinib, it suppressed HER3 activation and promoted strong antitumor effect in ALK-rearranged tumors with mesenchymal features in a xenograft tumor model." (PMID 39551860, 2024). "In patient TFCP2-HD-4, the intragenic ALK deletion and homozygous CDKN2A loss were not detectable in the early tumor but in the local recurrence 28 months later." (PMID 38168093, 2024). "The CheckMate026 study conducted a comparison between nivolumab and platinum-based chemotherapy in patients diagnosed with stage IV NSCLC who had PD-L1 expression levels greater than 5% in their tumor cells and did not have EGFR- or ALK-activating mutations." (PMID 39027681, 2024).
tumor (continued). "For example, in the absence of therapy, the proliferation of tumor cells in the H3122 xenograft model of ALK+ NSCLC is randomly distributed through tumor parenchyma." (PMID 39001467, 2024). "Nivolumab plus ipilimumab is indicated in the USA and other countries for the first-line treatment of adults with metastatic NSCLC with PD-L1 ≥ 1% and no EGFR or ALK genomic tumor aberrations." (PMID 38893141, 2024). "The discoveries of tumor-driver genes such as epidermal growth factor receptor (EGFR), anaplastic lymphoma kinase (ALK), mesenchymal-epithelial transition (MET), and c-ros oncogene 1 (ROS1) in NSCLC have recommended TKIs as the first-line option for patients with advanced stage disease." (PMID 38927911, 2024). "If we found features for ALK‐positive NSCLC, we believed the tumor marker may predict ALK‐positive NSCLC with reference to patient background." (PMID 38400801, 2024). "MDK/ALK/ALP and GAS/MERTK/AXL interactions between tumor cells and endothelial cells/fibroblasts may be potential therapeutic targets for PTC." (PMID 37733241, 2023). "The ALK ligand, ALKAL2, has higher expression in non-MYCN- versus MYCN-amplified tumours, although it is still capable of enhancing MYCN-driven neuroblastoma even in the absence of hotspot ALK mutations." (PMID 37414143, 2023). "It is not clear if this can be considered a real side effect of ALK target therapy or if it depends more on the peculiar biomolecular characteristics of ALK-rearranged neoplasia." (PMID 38201357, 2023). "The lack of consensus regarding the management of PCNS ALK-positive ALCL impedes standardized therapy for this rare tumor, potentially leading to unfavorable outcomes." (PMID 38137585, 2023). "In ALK (anaplastic lymphoma kinase)-positive non-small cell lung cancer, PFKFB3 is a downstream molecule of ALK-STAT3 signaling pathway that positively regulates the glycolysis level and plays a carcinogenic role in tumor cells." (PMID 36973739, 2023). "For instance, some studies suggest that the anaplastic lymphoma kinase (ALK) inflammasome component is required for NLRP3 activation in macrophages and that NLRP3 inflammasome activation might play a pro-tumor role through the IL-18 effector cytokine." (PMID 37205092, 2023). "The reported tumours originated in the middle and lower segments of the CBD, with an average size of approximately 3.5 cm × 3.0 cm and tumour cells expressing smooth muscle actin (SMA), vimentin and ALK." (PMID 36855132, 2023). "The median percentage of viable tumor in resected patients without known tumor EGFR/ALK alterations was 51% (range 0–95.5%) in the Nivo+CT arm (n = 17) compared with 2.8% (range 0–94.4%) in the Ipi+Nivo+CT arm (n = 14)." (PMID 36928818, 2023). "In a cohort of 50 French patients, the dynamic change in ALK‐positive circulating tumor cells (CTC), as estimated by FISH, did not significantly associate with response to treatment." (PMID 37243883, 2023). "In patients without known tumor EGFR/ALK alterations, MPR rates were 41.2% (7/17) and 62.5% (10/16) in the Nivo+CT and Ipi+Nivo+CT groups, respectively." (PMID 36928818, 2023). "Neoadjuvant or perioperative chemotherapy plus an ICI would now be the preferred approach for resectable stage III NSCLC for the majority of patients unless they have tumours with molecular abnormalities, such as EGFR or ALK, or have contraindications to the use of an ICI." (PMID 37999109, 2023). "Oncogenic mutation drivers such as epidermal growth factor receptor (EGFR), anaplastic lymphoma kinase (ALK), and repressor of silencing 1 (ROS-1) can alter the immune tumour microenvironment, which may induce anti-PD1/PD-L1 resistance." (PMID 38132403, 2023). "No relevant differences were observed in tumor size, location, or anatomical type between the ALK-positive and ALK-negative groups." (PMID 36823653, 2023).
tumor (continued). "For example, we detected sensitivity to HSP90 inhibition in both normal epithelial and cancer cell cultures, corroborating the finding that HSP90 inhibition induces toxicity without tumor‐selective response in patients carrying ALK‐rearranged NSCLC." (PMID 36423211, 2023). "The primary tumor and thigh recurrence at 6 years were negative for ALK rearrangement by FISH or IHC (next-generation sequencing [NGS] failed because of decalcification)." (PMID 38096470, 2023). "It is not uncommon that neoplasm cells of ES-RMS were immunoreactivity for ALK protein according to the previous studies, so was confirmed in our present case, which is rarely seen in the other variants of RMS." (PMID 36998041, 2023). "Using both ALK overexpression and knockdown, we also demonstrate a role for ALK in the modulation of proliferation, apoptosis, migration, and induction of cancer stem cell (CSC) features in Em Ca cell lines and primary tumor samples." (PMID 37592266, 2023). "Nivolumab plus ipilimumab is approved in the United States as first-line treatment for adults with metastatic NSCLC with no EGFR/ALK aberrations and tumor PD-L1 expression ≥ 1%, and in Japan as first-line treatment regardless of tumor PD-L1 expression." (PMID 37548831, 2023). "Notably, MDK/LRP1, MDK/ALK, GAS6/MERTK, and GAS6/AXL between fibroblasts and tumor cells exhibited a higher communication possibility than that between fibroblasts and thyrocytes." (PMID 37733241, 2023). "Moreover, other tumor suppressors, such as SHP1 and miR-150, are also silenced in ALK+ ALCL cells via DNA methylation." (PMID 37894456, 2023). "Based on these results, we think that the combination therapy enhances the anti-tumor effect without increasing the side effects on non-cancerous cells and that it is a feasible therapeutic approach for ALK+ ALCL." (PMID 37894456, 2023). "Histopathological findings showed ALK‐negative, EGFR L858R mutation‐positive invasive adenocarcinoma with a programmed death‐ligand 1 tumor proportion score of less than 1%." (PMID 36605695, 2023). "A second ‘ALK Independent’ Group 2 contained eleven of the 41 patients (27%), characterized by a lack of correlation between circulating tumor ALK VAF and clinical response." (PMID 37147298, 2023). "One tumor expressed in addition AE1/AE3, MUC4, synaptophysin, chromogranin, and ALK." (PMID 37097347, 2023). "We found MPR and pCR rates of 41.2% and 23.5%, respectively, and a 12-month and 24-month EFS of 100% and 71%, respectively, in patients without known tumor EGFR/ALK alterations." (PMID 36928818, 2023). "NPM::ALK-STAT3 signaling in ALK+ ALCL induces expression of transforming growth factor beta (TGF-β), IL-10, and cell surface receptor PD-L1 (CD274, B7H1), creating an immunosuppressive tumor microenvironment." (PMID 37810974, 2023). "Therapeutic strategies that target insulin/AMPK signaling and/or multi-TKI inhibitors that target ROS, ALK, KIT, FAK, TIE2, SRC, etc., may specifically target the tumor biology of these poorest-prognosis patients." (PMID 38086377, 2023). "In the last few years more and more drugs, such as TRK, ALK, checkpoint, and BRAF, as well as FGFR, inhibitors have been or are being evaluated in basket clinical trials, with some of them already formally approved as tumor agnostic therapies." (PMID 38098111, 2023). "Histopathological findings revealed ALK‐negative, EGFR L858R mutation‐positive invasive adenocarcinoma with a PD‐L1 tumor proportion score of less than 1%." (PMID 36605695, 2023). "These tumours also had similar detection rates for EGFR mutations and for RET, ROS1, ALK and MET oncogenic isoforms compared with tumours in never-smokers, which suggests that they have a similar aetiology and pathogenesis." (PMID 37046096, 2023). "In addition, many well-characterized tumor-promoting proteins, including those with roles in metastasis, were increased on the cell surface, including c-MET, EGFR, VEGFR, ALK and ITGα5." (PMID 36674782, 2023).